TRIM22 (tripartite motif containing 22)
Diseases named in the same sentence as TRIM22 in open-access papers (continued):
Sharing a sentence is not in itself a finding about the gene and the disease.
breast cancer (4 papers, 2017 to 2025). A primary or metastatic malignant neoplasm involving the breast. "One study reported TRIM22 downregulation in breast cancer cell lines and tissues compared with non-malignant mammary epithelial cell lines and normal breast tissues." (PMID 33879231, 2021). "One reported showed TRIM22 downregulationg in breast cancer cell lines and tissues compared with non-malignant mammary epithelial cell lines and normal breast tissues." (PMID 28977927, 2017).
chronic hepatitis B (4 papers, 2014 to 2023). "A total of 765 Chinese Han subjects were enrolled: 293 patients were presented with chronic hepatitis B (CHB), 224 were asymptomatic HBV carriers, 248 had self-limited HBV infection, and all of them were recruited for TRIM22 SNPs genotyping." (PMID 24596578, 2014).
colon cancer (4 papers, 2020 to 2024). "In sum, our data demonstrated that the silencing of LINC01207 inhibited cell proliferation and invasion in colon cancer by regulating the miR-3125/TRIM22 axis, indicating an oncogenic role of LINC01207." (PMID 33299853, 2020). "In conclusion, LINC01207 exerts an oncogenic role in the progression of colon cancer by absorbing miR-3125 to modulating TRIM22 expression." (PMID 33299853, 2020). "Rescue assays revealed that miR-3125 inhibitor or TRIM22 overexpression significantly reversed the repressive role of LINC01207 knockdown in colon cancer cell proliferation and invasion." (PMID 33299853, 2020). "Collectively, TRIM22 is a target gene of miR-3125 in colon cancer cells, which could be regulated by LINC01207." (PMID 33299853, 2020). "Finally, the rescue assays were performed to further evaluate the effect of LINC01207/miR-3125/TRIM22 axis on the progression of colon cancer." (PMID 33299853, 2020). "Therefore, we speculate that LINC01207 exerts an oncogenic role in the development of colon cancer by regulating the miR-3125/TRIM22 axis." (PMID 33299853, 2020). "Five TRIM expression was significantly upregulated (TRIM14, TRIM15, TRIM24, TRIM29, and TRIM31), and the other five TRIM genes showed decreased expression (TRIM1, TRIM3, TRIM9, TRIM22, and TRIM73) in both colon cancer (COAD) and rectal cancer (READ)." (PMID 38769340, 2024). "In this study, we evaluated the expression of TRIM16, TRIM22, and TRIM29 in colon cancer." (PMID 37671092, 2023).
hepatocellular carcinoma (4 papers, 2013 to 2025). A malignant tumor that arises from hepatocytes. "Inhibition of Trim22 increased cellular proliferation in human hepatoma cell lines, whereas overexpression of Trim22 decreased cellular proliferation in hepatoma cell lines." (PMID 31979338, 2020). "Because Trim22 is related to interferon signaling, there is a possibility that cell proliferation was influenced by this signaling by HBV in hepatoma cell lines." (PMID 31979338, 2020).
hepatitis B (3 papers, 2011 to 2016). "For instance, TRIM22 has experienced positive selection in these same retroviral targeting motifs, and while this gene may be relevant to retroviral infection, it also has activity against hepatitis B and picornaviruses." (PMID 22144910, 2011).
lupus (3 papers, 2012 to 2024). "TRIM22 expression is also downregulated in CD4+ T cells from patients with active systemic lupus erythematosus (SLE)." (PMID 22649727, 2012).
measles (3 papers, 2016 to 2022). A highly contagious viral infection caused by the measles virus. "Single nucleotide polymorphisms (SNPs) on TRIM5 and TRIM22 genes have been implicated to play an important role in several infections disease including HIV, HBV, measles and rubella vaccination." (PMID 36042495, 2022). "Single nucleotide polymorphisms (SNPs) at TRIM5 and TRIM22 genes have been implicated in several infections such as HIV, HBV, and measles and rubella vaccination." (PMID 27590274, 2016).
melanoma (3 papers, 2023 to 2025). A malignant, usually aggressive tumor composed of atypical, neoplastic melanocytes. "At the same time, other functions and associated mechanisms of TRIM22 in melanoma warrant further exploration." (PMID 40593126, 2025). "Through physical interaction, TRIM22 promoted p21 K63-linked ubiquitination and subsequent proteasomal degradation in melanoma." (PMID 40593126, 2025). "For example, in melanoma patients, lower TRIM22 expression is correlated with shorter survival times, whereas in non-small-cell lung cancer, TRIM22 overexpression is associated with poorer survival outcomes." (PMID 40075566, 2025). "For instance, TRIM22 is downregulated in melanoma, where its reduced expression is associated with cancer progression and poor prognosis." (PMID 40075566, 2025). "In this study, we aimed to elucidate the role of TRIM22 in melanoma and the underlying mechanism that drives melanoma progression." (PMID 40593126, 2025). "While TRIM22 is implicated in diverse cellular functions and plays distinct role in different cancers, its contribution to melanoma progression and the underlying mechanisms remains largely underexplored." (PMID 40593126, 2025). "We provide a novel mechanism in which TRIM22 regulates p21 by functioning as an E3 ligase and induces K63-linked ubiquitination of p21 to regulate melanoma cell cycle progression." (PMID 40593126, 2025). "Lastly, these data implicated that TRIM22 was decreased in melanoma and low TRIM22 correlated with poor prognosis of patients." (PMID 37415153, 2023). "In the present study, we found that TRIM22 was down-regulated in melanoma samples relative to normal tissues, which was associated with poor prognosis of patients." (PMID 37415153, 2023). "Melanoma cells with TRIM22 deficiency depended on KAT2A to enhance malignant progression, including proliferation, migration, and in vivo growth." (PMID 37415153, 2023). "In this study, we report the down-regulation of TRIM22 in melanoma samples, which is associated with the prognosis of patients." (PMID 37415153, 2023). "Herein, we discovered that TRIM22 promoted the proliferation of melanoma cells which might be linked to its regulation of cell cycle progression." (PMID 40593126, 2025). "To investigate the mechanism by which TRIM22 promotes melanoma proliferation, we used flow cytometry to determine the effect of TRIM22 on the cell cycle progression, as cell cycle is a critical event for proliferation." (PMID 40593126, 2025). "In general, these results verified the overexpression of TRIM22 in melanoma and its possible implication as a potential biomarker in melanoma progression." (PMID 40593126, 2025). "In this study, we found that expression of TRIM22 was abnormally upregulated in melanoma tissues, correlating with tumor stages." (PMID 40593126, 2025). "This novel insight contributes to a more comprehensive understanding of the working mechanism and oncogenic functions of TRIM22, and a new regulation mechanism of p21 and cell cycle in melanoma." (PMID 40593126, 2025). "Given these varying functions of TRIM22 in different cancers and limited investigation in melanoma, there is a need for a clear understanding of the role of TRIM22 in melanoma and the underlying regulatory mechanism." (PMID 40593126, 2025). "Taken together, our results illustrate that TRIM22 functions as a tumor-promoting factor in melanoma and reveal that it promotes cell proliferation by targeting p21 for degradation." (PMID 40593126, 2025). "Collectively, these results provide compelling evidence that TRIM22 can promote melanoma proliferation in vitro." (PMID 40593126, 2025). "To confirm the upregulated expression of TRIM22 in melanoma at protein level, we utilized IHC data from the HPA database." (PMID 40593126, 2025). "Accordingly, our findings provide new insight into the function and involvement of TRIM22 in melanoma, which would contribute to the overall understanding of TRIM family function in tumors." (PMID 40593126, 2025).
melanoma (continued). "Beginning with the analysis of public databases and clinical samples, we found that TRIM22 was highly upregulated in melanoma and its expression level was correlated with the clinical stage." (PMID 40593126, 2025). "Consistent with previous reports, these results further consolidated the function of TRIM22 as an E3 ligase in tumor progression, including melanoma." (PMID 40593126, 2025). "Such significantly high expression suggests a functional role in tumor progression; thus, we performed a viability assay to assess to role of TRIM22 in melanoma cell proliferation." (PMID 40593126, 2025). "Subsequently, we investigated the effect of TRIM22 on melanoma cell proliferation via different methods, including the CCK-8 assay, crystal violet staining, colonogenic assay and EdU assay." (PMID 40593126, 2025). "We demonstrated that TRIM22 expression was significantly upregulated in melanoma, which positively correlated with melanoma progression and patient tumor stage." (PMID 40593126, 2025). "Given that the regulation of p21 through K63-linked ubiquitination is a characteristic function of E3 ligases, these results suggest that TRIM22 is an E3 ligase of p21 and promotes the proliferation of melanoma cells through the ubiquitination of p21." (PMID 40593126, 2025). "Taken together, these results clarified that TRIM22 regulates the proliferation of melanoma cells at least partially through targeting its substrate p21 for degradation to promote cell cycle progression." (PMID 40593126, 2025). "The KAT2A is a bona fide target of TRIM22, and TRIM22 deficiency promoted the accumulation of KAT2A proteins in melanoma." (PMID 37415153, 2023). "Together, our study revealed the novel role of the TRIM22/KAT2A axis in modulating melanoma progression and provided essential targets for treatment." (PMID 37415153, 2023). "To further confirm the biological role of TRIM22 in melanoma, we transfected M14 cells with TRIM22-shRNA lentivirus to knock down TRIM22." (PMID 37415153, 2023). "The Forest plot revealed that the TRIM22 level was an independent prognostic factor for melanoma patients, as compared to TNM stages." (PMID 37415153, 2023). "Collectively, these results show that TRIM22 downregulation promotes melanoma progression in vitro and in vivo." (PMID 37415153, 2023). "Here, we utilized the bioinformatic methods to confirm that TRIM22 is decreased in melanoma than normal tissues." (PMID 37415153, 2023). "To assess the TRIM22 expressions in melanoma samples, we first downloaded the mRNA data of TRIM22 from the TCGA-SKCM cohort." (PMID 37415153, 2023). "The results showed that melanoma tissues presented lower expression of TRIM22 while benign nevus showed higher expressions." (PMID 37415153, 2023). "This project aims to investigate the biological function of TRIM22 in melanoma and provide novel therapeutical targets." (PMID 37415153, 2023). "Meanwhile, we observed that low levels of TRIM22 increased, and ectopic expressions of TRIM22 decreased the colony formation abilities of melanoma cells." (PMID 37415153, 2023). "Targeting TRIM22 favors melanoma cell migration, proliferation, and tumor development in vitro and in vivo." (PMID 37415153, 2023). "Targeting TRIM22-induced melanoma progression, including cell colony formation, stemness, and migration capacities." (PMID 37415153, 2023). "TRIM22 deficiency mediates the accumulations of KAT2A and depended on KAT2A to promote melanoma progression." (PMID 37415153, 2023). "Compared to adjacent normal tissues, TRIM22 protein levels were both down-regulated in melanoma sections." (PMID 37415153, 2023). "Intriguingly, wound-healing assay further suggested that TRIM22 knockdown enhanced the migrated rates of A375 cells, and TRIM22 overexpression suppressed melanoma cell migration." (PMID 37415153, 2023).
melanoma (continued). "These facts indicate that targeting TRIM22 may be a promising therapeutic target for the treatment of melanoma patients and the establishment of the TRIM22-p21 axis will become an important foundation in the development of new treatment strategies." (PMID 40593126, 2025). "Mechanistically, overexpression of TRIM22 could promote the proliferation of melanoma cells by accelerating cell cycle progression through degrading p21 via the 26S proteasome system." (PMID 40593126, 2025). "Taken together, our study identifies TRIM22 as an oncogenic driver that could be considered a potential therapeutic target for melanoma treatment." (PMID 40593126, 2025). "Taken together, these results demonstrated that TRIM22 could promote melanoma cell proliferation via regulating the cell cycle progression." (PMID 40593126, 2025). "Functional analysis demonstrated that TRIM22 promoted melanoma cell proliferation in vitro." (PMID 40593126, 2025). "Overall, our findings elucidated that TRIM22 acted as an E3 ligase targeting p21 for degradation to promote melanoma progression, which improved the understanding of TRIM22 function and provided more clues for developing TRIM22 as a potential target for malignant melanoma treatment." (PMID 40593126, 2025). "Furthermore, we found that in malignant melanoma, TRIM22 expression is negatively correlated to the level of p21, an inhibitor of cell cycle." (PMID 40593126, 2025). "Next, we explore the impact of TRIM22 on the viability of melanoma cells." (PMID 40593126, 2025). "Tripartite motif-containing 22 (TRIM22), an E3 ubiquitin ligase of the tripartite motif (TRIM) family, is implicated in tumorigenesis, but its working mechanism remains poorly understood in melanoma." (PMID 40593126, 2025). "Further investigation of IHC from clinical melanoma patients revealed significantly elevated expression of TRIM22 in stage II and stage III tumors, corroborating our initial finding of a direct association of TRIM22 with tumor stage." (PMID 40593126, 2025). "Last, of all, we also explored the in vivo roles of TRIM22 in melanoma." (PMID 37415153, 2023). "TRIM22 inhibition enhances melanoma proliferation and migration." (PMID 37415153, 2023). "Nevertheless, the role of TRIM22 in melanoma is still indefinite." (PMID 37415153, 2023). "The in vitro or in vivo assays were used to explore the functions of TRIM22 in melanoma." (PMID 37415153, 2023). "Furthermore, we categorized the melanoma patients into TRIM22-high and TRIM22-low groups according to the median data of TRIM22." (PMID 37415153, 2023). "However, the role of TRIM22 in melanoma remains unclear; hence, we aim to investigate the expression and functional relevance of TRIM22 in melanoma." (PMID 40593126, 2025). "Moreover, TRIM22 promoted cell cycle progression and proliferation of melanoma cells in vitro." (PMID 40593126, 2025). "To further determine whether TRIM22 exerts the role of promoting melanoma cell proliferation through p21, we overexpressed TRIM22 in p21-knockdown A375 cells and investigated the impact on the proliferation of melanoma cells." (PMID 40593126, 2025). "Our result revealed that TRIM22 overexpression promoted the proliferation of melanoma cells while the knockdown inhibited melanoma cell proliferation, implying that the high expression of TRIM22 observed in public and clinical data studies could be linked to melanoma progression." (PMID 40593126, 2025). "To compare melanoma expression with common acquired nervus we used datasets from the GEO database (GSE98394) and observed that the expression of TRIM22 was significantly higher in primary melanoma than in common acquired nevus (p < 0.0001)." (PMID 40593126, 2025). "The results also showed that the expression of TRIM22 in melanoma tissue was significantly higher compared to normal skin tissues." (PMID 40593126, 2025). "TRIM22 mediates the ubiquitination and degradation of KAT2A proteins in melanoma." (PMID 37415153, 2023).
melanoma (continued). "Moreover, we discovered that overexpression of TRIM22 could not bring further boost of cell proliferation in p21 knockdown melanoma cells, indicating an epistatic role of p21 to TRIM22." (PMID 40593126, 2025). "However, the role of TRIM22 in melanoma progression has never been uncovered." (PMID 37415153, 2023).
non-small cell lung carcinoma (3 papers, 2017 to 2025). A group of at least three distinct histological types of lung cancer, including non-small cell squamous cell carcinoma, adenocarcinoma, and large cell carcinoma. "TRIM22 expression is associated with poor prognosis in non-small cell lung cancer." (PMID 32226386, 2020). "TRIM22 protein was upregulated in 70/126 (55.6%) non-small cell lung cancer tissues compared with normal lung tissue." (PMID 28977927, 2017).
AIDS (2 papers, 2019 to 2024). A syndrome resulting from the acquired deficiency of cellular immunity caused by the human immunodeficiency virus (HIV). "Changes in TRIM22 expression are also associated with diseases such as MS, cancer, and other AIDs." (PMID 39840076, 2024).
chronic hepatitis (2 papers, 2011 to 2014). An active inflammatory process affecting the liver for more than six months. "Liver biopsies from patients with mild chronic hepatitis Cand no fibrosis showed a marked increase in TRIM22 expression (foldchange 17.0, p<0.001)." (PMID 21359205, 2011).
chronic myeloid leukemia (2 papers, 2020 to 2024). "However, subsequent studies confirm that the silencing of TRIM22 decreases chronic myeloid leukemia K562 cell proliferation and invasion and triggers cell cycle arrest and apoptosis, indicating an oncogenic role of TRIM22." (PMID 33299853, 2020). "Besides, TRIM22 knockdown inhibited the activation of PI3K/Akt/mTOR pathway by decreasing the level of the phosphorylated form p‐Akt and p‐mTOR in chronic myeloid leukemia." (PMID 38468469, 2024).
Cirrhosis (2 papers, 2006 to 2018). A chronic disorder of the liver in which liver tissue becomes scarred and is partially replaced by regenerative nodules and fibrotic tissue resulting in loss of liver function. "A small set of genes (ISG20, IFI16, TRIM22, STAT5A) were also highly up-regulated in nearly all samples, including ethanol-cirrhotic livers, suggesting these may play a role in an inflammatory response related to cirrhosis development regardless of etiology." (PMID 17121680, 2006).
Crohn disease (2 papers, 2020 to 2022). A gastrointestinal disorder characterized by chronic inflammation involving all layers of the intestinal wall, noncaseating granulomas affecting the intestinal wall and regional lymph nodes, and transmural fibrosis. "Meanwhile, only one early-onset Crohn’s disease (CD) patient had a TRIM22 variant that was consistent with the previous result." (PMID 35609018, 2022).
esophageal squamous cell carcinoma (2 papers, 2025). Esophageal squamous cell carcinoma (ESCC) is a type of esophageal carcinoma (EC) that can affect any part of the esophagus, but is usually located in the upper or middle third. "Additionally, we detected TRIM22 expression in the human esophageal squamous cell carcinoma cell lines." (PMID 40075566, 2025). "Based on these findings, we hypothesize that Lyc.HCL may exert its anti-esophageal squamous cell carcinoma effects through the targeting of TRIM22." (PMID 40075566, 2025). "High expression of TRIM22 in esophageal squamous cell carcinomas (ESCC), correlates positively with cell proliferation, metastasis and invasion." (PMID 40593126, 2025). "However, the role of TRIM22 in esophageal squamous cell carcinoma (ESCC) remains unexplored." (PMID 40075566, 2025).